TNF (tumor necrosis factor)
Diseases named in the same sentence as TNF in open-access papers (continued):
Sharing a sentence is not in itself a finding about the gene and the disease.
depression (continued). "In addition, resveratrol supplementation reduces levels of pro-inflammatory cytokines (IL-1β, IL-2, IL-4, IL-6, TNF-α) in animal models of depression." (PMID 30200269, 2018). "Major depression patients have abnormal levels of IL-6 and TNF-α, and increased Hp." (PMID 30360353, 2018). "Furthermore, in chronic mild stress (CMS) model of depression, the concentrations of IL-1β, IL-6, IL-18 and TNF-a in the brain or serum were enhanced." (PMID 30390665, 2018). "The activated M1 phenotype expresses CD11b, CD68, and pro-inflammatory cytokines, including interleukin (IL)-1β, tumor-necrosis factor (TNF)-α, and IL-6, which have been extensively reported to induce oxidative stress, neuronal damage, neurotransmitter dysfunction, and depression-like behavior." (PMID 30248907, 2018). "However, when the mice were administered infliximab, an anti-TNF-α antibody, depression symptoms were reduced." (PMID 30200269, 2018). "However, the present study did not replicate previous findings that have indicated increased gene expression or involvement of IL-6, IFN-γ, or TNF-α in depression." (PMID 29064428, 2017). "Another study found that XPJY has the better effect on improving learning and memory ability in depression rats than sertraline, which might he related to reduce the inflammatory factors level, such as IL-1β, IL-6 and TNF-α, in serum and hippocampus." (PMID 28118829, 2017). "These two hypotheses claim that the increased production of pro-inflammatory cytokines (TNF alpha) is known to affect the brain both, directly and indirectly, thereby increasing symptoms of depression." (PMID 29233119, 2017). "Our earlier studies have shown that learning and memory ability in depression rats might be related to reduce the inflammatory factors level, such as IL-1β, IL-6 and TNF-α, in serum and hippocampus." (PMID 28118829, 2017). "Additionally, different studies have also reported increased circulating levels of pro-inflammatory cytokines like IL 1, IL 6 and TNF α in major depression patients." (PMID 28580183, 2017). "Significantly higher concentrations of TNF-α and IL-6 in depressed subjects compared with control subjects have also been determined by means of a large meta-analysis of studies measuring cytokine concentration in patients with major depression." (PMID 29109914, 2017). "TNF-α exerts robust acute effects on brain function in the degenerating brain and is highly relevant for the illness-induced exacerbations of brain dysfunction, including depression, delirium, and POCD." (PMID 29137628, 2017). "We observed a direct correlation between sera TNF-α levels and the severity of depression symptoms." (PMID 26732584, 2016). "We further elaborate on the role of TNF-α in depression with autoimmune diseases." (PMID 27187381, 2016). "TNF-α may contribute to the pathophysiology of depression by activating the hypothalamic–pituitary–adrenal (HPA) axis and neuronal serotonin transporters and by stimulating the enzyme indoleamine-2,3-dioxygenase (IDO), which causes tryptophan depletion." (PMID 27918465, 2016). "Notably, a proof-of-concept study examined infliximab, a TNF-α blocker in patients with treatment-resistant depression." (PMID 28082989, 2016). "Whether the raised IL10 production is a response to the inflammation associated with depression in our cohort, we found raised IL6 and TNFα only in the hip fracture patients who developed depressive symptoms, remains to be shown but is one possibility." (PMID 26112234, 2016). "Among females, higher maternal TNF-α:IL-10 was associated with reduced odds of depression (OR=0.51; CI=0.32, 0.81), whereas, among males, high maternal TNF-α:IL-10 was associated with elevated odds of depression (OR=1.86; CI=1.02, 3.39)." (PMID 27244231, 2016). "However, it is still unclear, and many studies of depression are currently being connected to the TNF-α level." (PMID 27187381, 2016).
depression (continued). "The relationship between TNF-α and depression in patients with autoimmune disease may be explained by two main theories." (PMID 27187381, 2016). "The higher consumption of serotonin and its precursor tryptophan due to IDO activation may justify the reduced availability of serotonin and link TNF-α to depression." (PMID 26732584, 2016). "It is well known that TNF-α blockers are very effective in the treatment of chronic inflammatory disorders like psoriasis, Crohn’s disease (CD), and ankylosing spondylitis (AS), which can co-exist with depression." (PMID 27187381, 2016). "However, when considering the TNF-α to IL-10 ratio, a measure of the ratio of pro- to anti-inflammatory loading, maternal immune effects on offspring depression differed significantly by sex (χ2=13.9, degrees of freedom=4, P=0.008)." (PMID 27244231, 2016). "In this review article, we focus on recent evidence linking TNF-α and MDD looking at data from animal and clinical studies, illustrating the pathophysiological role, susceptibility and its therapeutic application in depression." (PMID 27187381, 2016). "There are three leading mechanisms which might relate the TNF-α system to the pathophysiology of depression." (PMID 27187381, 2016). "Of particular interest in depressive disorders are the cytokines IL-β, IL-6, and TNF-α." (PMID 26775294, 2016). "Here, we tested the hypothesis that systemic upregulation of TNF-α induces neuroinflammation and behavioral changes relevant to depression." (PMID 26290874, 2015). "Some authors suggest that the virus may be related to the pathogenesis of depression inducing pro-inflammatory cytokines production such as IL-1, TNF-alpha and IL-6." (PMID 26018525, 2015). "IL-6 and TNFα appeared to be the most consistently elevated cytokines in the studies conducted on depressive patients (see meta-analysis) as well as in animal models of depression." (PMID 26477946, 2015). "In depression, specific subgroups of patients were shown to respond to anti-TNF treatment." (PMID 28781965, 2015). "However, the mechanisms by which TNF mediates changes in behaviour, and its potential role in both sickness and depression, are yet to be explored." (PMID 26147001, 2015). "In this series of experiments, we tested whether peripheral administration of TNF-α in mice is able to induce neuroinflammation as well as behavioral changes relevant to human depression." (PMID 26290874, 2015). "Similar to the current results, in animal models of sickness behavior, prolonged production of TNF-α, IL-6, and IL-1β can also lead to a variety of symptoms including fat and muscle wasting and behavioral changes similar to symptoms of depression that also occur in cancer patients." (PMID 25945105, 2015). "This has led to the conclusion that TNF-α is involved in the pathophysiology of depression." (PMID 26690116, 2015). "Numerous studies have reported that circulating pro-inflammatory cytokines, such as interleukin-1 beta (IL-1β), IL-6, interferon gamma (IFN-γ), and tumor necrosis factor alpha (TNF-α), may be associated with some forms of major depression." (PMID 26521132, 2015). "There are data that depressive episodes are accompanied by an increased sensitization of immune-inflammatory pathways and that the number of depressive episodes is correlated with immune-inflammatory markers such as TNF-α and neopterin." (PMID 25880127, 2015). "A correlation analysis of the Hospital Anxiety and Depression Scale score and cytokine levels revealed positive associations with the domain of anxiety/depression with IL-6, IL-1beta and TNF-alpha and a negative correlation with IL-10." (PMID 26300773, 2015). "Furthermore, patients with painful neuropathy have increased serum expression of TNF and IL-2 (a T cell activator), with the highest levels of TNF found in patients with comorbid depression." (PMID 25986444, 2015).
depression (continued). "Furthermore, patients with SSRI-resistant depression show significantly higher levels of TNF- α in comparison to healthy controls." (PMID 26445118, 2015). "Increased levels of inflammatory markers such as the cytokines CRP, IL-6 and TNF-α have been measured in patients with depression, regardless of a causal link between depression and inflammation." (PMID 26231223, 2015). "Like stressors, which may engender features of depressive disorder in rodents, the systemic administration of proinflammatory cytokines such as interleukin-1β (IL-1β) and tumor-necrosis factor-α (TNF-α) increases hypothalamic-pituitary-adrenal (HPA) activity." (PMID 26417153, 2015). "Similarly, most of the studies in the field are focused on definite cytokines including interleukin- (IL-)1β, IL-6, and tumor necrosis factor-α (TNF-α) since the changes in circulating IL-1β, IL-6, and TNF-α were revealed in patients with major depression." (PMID 24999483, 2014). "Correlation analysis between HADS score and cytokine levels revealed a positive association of anxiety and/or depression with IL-1β, IL-6, IL-8, and TNF-α and a negative correlation with IL-10." (PMID 25309921, 2014). "A role for TNF-α in depression-like behavior has been directly shown." (PMID 23634700, 2013). "In further support of a role for TNF-α in depression, human patients afflicted with plaque psoriasis showed significant improvement in Beck Depression Inventory and Hamilton Rating Score for depression when treated with the TNF neutralizing drug Etanercept." (PMID 23634700, 2013). "Changes in Hamilton Depression Rating Scale scores were significantly associated with changes in IL-6 (P = 0.003) levels; changes in Young Mania Rating Scale scores were significantly associated with changes in CRP (P = 0.006) and TNF-α (P = 0.039) levels." (PMID 23826157, 2013). "Furthermore, differences between MDD and BPD were seen for matrix-associated growth factors APP and SPARC, immune gene TNF, and transcription factors CREB1, NFKB1, and NR3C1 when controlling for depression severity, age, and medication use." (PMID 24143878, 2013). "Depression is associated with an altered balance in the Th1/Th2 ratio, that is, higher pro-inflammatory Th1 cytokines (IL-1, IL-12, INF-γ), higher pro-inflammatory monocytic cytokines (IL-6, TNF-α), and lower anti-inflammatory Th2 cytokines (IL-4, IL-10)." (PMID 22778932, 2012). "The inflammation in depression, which is characterized by increased levels of cytokines like interleukin-1 and 6 (IL-1, IL-6), and tumor necrosis factor (TNF), may cause the occurrence of somatic symptoms of depression." (PMID 22839681, 2012). "Serum samples from 65 perimenopausal women, 41 with depression and 24 without depression, were assessed for serum IL-6, TNFα and IL-10 by conventional enzyme-linked immunosorbent assays." (PMID 22490187, 2012). "Moreover, both sIL-2R and TNF-α correlated significantly and positively with symptoms of depression, anxiety, and fatigue." (PMID 23082161, 2012). "Indeed, elevated levels of circulating pro-inflammatory cytokines, including TNFα, IL-6 and IL-1β, are frequently observed in patients with depression." (PMID 21306618, 2011). "It has been demonstrated that omega-3 fatty acids may modify depression symptoms by inhibiting proinflammatory cytokines, particularly IL-1β and TNFα." (PMID 21864357, 2011). "Dantzer and coworkers reported that interleukin-6, a major proinflammatory cytokine, was increased in the blood of depressed patients, and a recent meta-analysis concluded that only the basal levels of IL-6 and tumour necrosis factor-alpha (TNF-α) were significantly raised in major depression." (PMID 22216404, 2011). "In a model with depression as the dependent variable, adjusting for the MCFS score, 6MWD, FEV1%, BMI and FFMI did not markedly change the association between TNF-α and depression and it remained statistically significant." (PMID 21208443, 2011).
depression (continued). "Besides, we found from this study that MDPT somehow managed the decline of circulation TNF-α first, and subsequently the pain and depression impairment." (PMID 20937108, 2010). "It seems that the TNFα level related to depression or to pain may be regulated by the same mechanism." (PMID 20937109, 2010). "We challenge the widely held cytokine hypothesis of both cLBP and depression with the alteration of proinflammatory cytokine TNFα." (PMID 20937109, 2010). "In the prospective cross-sectional clinical study described here, we set out to determine whether comorbid depression might affect the TNFα serum level in patients with low back pain, or whether TNFα might regulate both pain and depression together." (PMID 20937109, 2010). "Concerning the role of TNFα in depression, a lot of studies demonstrated significantly higher TNFα levels in major depressive disorder patients compared with normal controls and a decrease of these levels after treatment with antidepressants, then reaching similar levels to healthy controls." (PMID 20937109, 2010). "As we know, the pro-inflammatory cytokine TNF-α plays a role both in pain and depression." (PMID 20937108, 2010). "Many separate studies have shown that the proinflammatory cytokine TNFα may play a role in the pathophysiology both of pain and depression." (PMID 20937109, 2010). "There are several plausible mechanisms that could explain these results and the relationship between pain, depression and TNFα." (PMID 20937109, 2010). "Our previous work and the present study, taken together, confirm that there is no causal relationship between the TNFα serum level and cLBP, just as there is no causal relationship between cytokine alterations in the blood and depressive disorders." (PMID 20937109, 2010). "After evaluation of depression level study group was divided into groups according to the mood status (A—without depression, B—mild depression, and C—severe depression), and serum concentration of TNF-α, sTNFs, leptin, and IL-6 were measured by ELISA." (PMID 19587822, 2009). "Results of the PDG-ACE analysis are consistent with the hypothesis that genetic background, via TNF and MTHFR, as well as environmental influences, via alcohol intake or consumption, are interacting elements of susceptibility in comorbid depression with AUD." (PMID 18822146, 2008). "We chose the TNF-α system as an issue of this review, because significant findings regarding its involvement in brain disorders - such as depression, narcolepsy, multiple sclerosis, Alzheimer’s and Parkinson’s disease - and psychopharmacology have been reported in several study reports." (PMID 19506720, 2008). "Intracerebroventricular microinfusion of TNF-α prevents the efficacy of desipramine while that of TNF-α antibody mimics the therapeutic effect of the antidepressant, providing further evidences that this cytokine plays a key role in the pathogenesis of depression." (PMID 17477857, 2007). "Although this principle originates outside the CNS, it is equally applicable to CNS disorders: in depression, elevated inflammatory markers may indicate a better response to cytokine inhibitors or glial‐targeting agents such as minocycline or anti‐TNF therapies." (PMID 41583906, 2026). "Additionally, elevated serum levels of proinflammatory cytokines (e.g., CRP, IL-6, TNF-α) in depression cross the blood-brain barrier to directly inhibit sleep-regulatory functions in the prefrontal cortex and hypothalamus, leading to sleep fragmentation and reduced slow-wave sleep 67-69." (PMID 41399386, 2026). "Notably, TNF‐α antagonists like infliximab have been tested in depression: a randomized controlled trial found that while infliximab overall did not outperform placebo, it significantly improved mood symptoms in the high baseline inflammation subgroup (CRP > 5 mg/L)." (PMID 41583906, 2026).
depression (continued). "Moreover, elevated inflammatory cytokines like interleukin-6 (IL-6) and TNF-α in depression patients may lead to muscle atrophy and weakness." (PMID 40469587, 2025). "Interestingly, even in human blood, cumulative meta-analysis revealed that there is no consistent association with IL-1β and TNFα whilst IL-6 showed significance with depression in humans." (PMID 40179065, 2025). "In addition, while most studies were purely descriptive, a subset integrated biological markers into NA models, revealing significant associations among fatigue, depression, sleep disturbances, and inflammatory biomarkers such as IL-6, CRP, and tumor necrosis factor-α." (PMID 40633921, 2025). "Furthermore, TNF antagonists have shown promise as adjunctive therapies to enhance antidepressant efficacy in treatment-resistant depression, and patients with MDD may also benefit from corticosteroids and NSAIDs." (PMID 40977685, 2025). "According to a recent concept, depression is characterized by the activation of the inflammatory response system, which results in increased production of proinflammatory cytokines such as interleukin (IL)-1b, IL-6, tumor necrosis factor-alpha (TNF-a), and prostaglandin E2 (PGE2)." (PMID 41541942, 2025). "Increased levels of pro-inflammatory cytokines like IL-6, tumor necrosis factor-α (TNF-α), and IL-1β, which are implicated in starting inflammatory processes, are influenced by the CNS through several mechanisms that affect organs and, in turn, lead to depression." (PMID 39859327, 2025). "Furthermore, growing evidence suggests that individuals with depression also exhibit elevated levels of circulating cytokines like IL-6, IL-1β, TNF-α, IFN-α, prostaglandin E2 (PGE2), and chemokine CCL2, as well as acute-phase proteins such as C-reactive protein (CRP)." (PMID 40573262, 2025). "Furthermore, chronic inflammation in depression activates pro-inflammatory cytokines like IL-6 and TNF-α, which not only contribute to the stress response but may also promote erythropoiesis by affecting the bone marrow environment." (PMID 39797347, 2025). "Given the role of TNF-α in depression, anti-TNF-α biologics may exert antidepressant effects." (PMID 39980978, 2025). "Future research examining level of depression and inflammatory protein concentrations in serum, saliva, cerebrospinal fluid and neuroimaging may assist in further extrapolating the relationship between TNF-α, IFN-γ, IL-6 and IL-10 and depression." (PMID 39867847, 2025). "Indeed, compelling evidence supports robust connections between depression and inflammation in IA, as depression drives peripheral and central inflammation and several cytokines implicated in depression also play influential roles in IA, including CRP, TNF-α and IL-6." (PMID 38749000, 2025). "In rodent models of diabetes-associated depression, activation of indoleamine 2,3-dioxygenase (IDO)—a key enzyme in tryptophan metabolism—results in decreased hippocampal serotonin (5-HT) levels and elevated pro-inflammatory cytokines such as TNF-α, IL-1β, and IL-6." (PMID 41299994, 2025). "Elevated levels of immune-related biomarkers, including IL-6, TNF-α, and C-reactive protein, have been consistently observed in individuals with clinical depression or suicidal behaviors, suggesting that immune dysregulation may underlie the pathophysiology of MDD and suicide risk." (PMID 41561993, 2025). "A recent longitudinal study of major depressive disorder identified a low baseline red blood cell count as a significant predictor of suicidal ideation trajectories, suggesting erythrocyte-mediated modulation of neuroinflammatory circuits (e.g., IL-6 and TNFα)." (PMID 40977981, 2025). "Notably, the group with both depressive disorder and chronic T. gondii infection exhibited a distinct cytokine profile characterized by significantly elevated TNF, IL-6, and IL-10 levels and significantly reduced IL-8 and MIF levels compared to the other groups." (PMID 40333139, 2025).